INS (insulin)
Diseases named in the same sentence as INS in open-access papers (continued):
Sharing a sentence is not in itself a finding about the gene and the disease.
diabetes (continued). "Dysregulation of insulin secretion or signaling results in systemic disorders driven not only by defective glucose uptake as in diabetes, but also by secondary microvascular and macrovascular damage, including, among others, retinal diseases." (PMID 41301488, 2025). "It has been tested in numerous pre-clinical models and clinical trials for rheumatoid arthritis, diabetes, COVID-19, and insulin sensitivity in patients with PCOS." (PMID 40563513, 2025). "The first DIGAMI trial (DIGAMI-1) was conducted in the 1990s to investigate the effects of intensive insulin therapy in diabetes patients following MI." (PMID 39913488, 2025). "Insulin is required for type 1 and refractory type 2 diabetes; thus, it is often an indicator of more severe diabetes." (PMID 39764343, 2025). "While these data highlight the translational potential of repurposing selected SMTKIs for diabetes management, validation in insulin-resistant animal models, human primary skeletal muscle cells, and ultimately clinical trials remains essential." (PMID 41155560, 2025). "Digital applications have the potential to enhance diabetes management, particularly in patients treated with insulin." (PMID 40661654, 2025). "Diabetes mellitus is a complex metabolic disorder characterized by chronic hyperglycemia resulting from defects in insulin production, insulin action, or both." (PMID 39856066, 2025). "Our study supports findings that reveal complications increase as diabetes continues and when people use high-intensity treatments such as insulin." (PMID 40837917, 2025). "Double diabetes treatment needs customized methods that combine insulin therapy with pharmaceutical medications chosen based on metabolic characteristics, heart health risks, and pancreatic cell functions." (PMID 40225541, 2025). "DM comprises two principal forms: type 1 diabetes (T1D), distinguished by an autoimmune degradation of pancreatic beta cells, and type 2 diabetes (T2D), predominantly linked to insulin resistance and decreased insulin secretion." (PMID 40913218, 2025). "Diabetes mellitus is a chronic metabolic disorder characterized by hyperglycaemia resulting from defects in insulin secretion, insulin action, or both." (PMID 40871679, 2025). "The primary outcome was prevalent diabetes, and secondary outcomes included fasting glucose, fasting insulin, HOMA-IR and 2 h OGTT results." (PMID 39982484, 2025). "The mean values of diabetes and insulin resistance markers were as follows: 85.60 ± 12.43 mg/dL for fasting glucose levels, 9.79 ± 5.60 μU/mL for insulin, and 5.41 ± 0.45% for HbA1c." (PMID 40362737, 2025). "In Type II Diabetes Mellitus (TIIDM), cells exhibit resistance to insulin, constituting 90% of all diabetes cases, and are treated with either synthetic or natural medications to overcome this resistance." (PMID 40601679, 2025). "Polysaccharides derived from various edible fungi have been shown to effectively improve hyperglycemia and diabetes through glucose metabolism regulation and enhanced insulin sensitivity and resistance." (PMID 41157089, 2025). "A 48-year-old male with Diabetes Mellitus treated with empagliflozin and insulin, presented with left thigh pain and anorexia." (PMID 40677793, 2025). "Contrary to that meta-analysis, results from randomized controlled trials (RCTs) examining the impact of vitamin E supplementation on insulin resistance and glycemic control in various forms of diabetes are contradictory." (PMID 39940428, 2025). "Diabetes mellitus is a group of disorders characterized by chronic hyperglycemia resulting from impaired insulin secretion, insulin action, or a combination of both." (PMID 41007307, 2025). "Diabetes mellitus is a metabolic disorder characterised by high glucose levels (hyperglycaemia) due to defects in insulin production, action or both." (PMID 41170150, 2025).
diabetes (continued). "This association remained significant, even after adjustment for age, sex, body mass index, plasma triglycerides, diabetes duration, daily insulin dose, time above the range of glucose levels, LSM and chronic kidney disease." (PMID 40083078, 2025). "Type 2 diabetes mellitus (T2DM) is a chronic metabolic disease characterized by insufficient insulin production, poor insulin action, or both." (PMID 40475993, 2025). "Fear of diabetes becoming a permanent condition, or of needing long-term insulin, was a powerful driver of change." (PMID 41141274, 2025). "Diabetes has emerged as one of the prevalent metabolic diseases globally, characterized by inadequate insulin secretion and/or action, leading to hyperglycemia." (PMID 40448105, 2025). "Diabetes mellitus (DM) is a chronic metabolic disorder characterized by sustained hyperglycemia resulting from inadequate insulin secretion and/or impaired insulin sensitivity." (PMID 41244042, 2025). "If I tell a diabetes patient about insulin needles, I can tell the patient I’ve poked myself with a needle before." (PMID 39787249, 2025). "Frontline staff described ‘fear’ and ‘under‐confidence’ in managing insulin and often relied on the expertise of specialist diabetes teams to make decisions around suitable adjustments." (PMID 40324886, 2025). "MST1 deletion has been proved to improve β-cell survival and insulin secretion in models of diabetes induced by streptozotocin (STZ) or HFD, and a combination of HFD and streptozotocin (HFS/STZ)." (PMID 40707469, 2025). "The availability of skilled staff with knowledge to understand insulin and diabetes management during acute illness was a key resource required for almost all functions." (PMID 40696540, 2025). "Insulin use among patients with diabetes added a 52% increase in hazard (HR: 1.52; 95% CI: 1.38 to 1.67; p<0.001)." (PMID 40967652, 2025). "The balance between dietary carbohydrate intake and glucose levels with proper insulin treatment has been the essential element of type 1 diabetes mellitus management." (PMID 41462804, 2025). "Exacerbating hepatic steatosis and insulin resistance decreased insulin secretion and induced diabetes." (PMID 41446042, 2025). "Diabetes Mellitus (DM): Diabetes mellitus, including both type 1 and type 2, is a chronic metabolic condition characterized by impaired insulin action or secretion." (PMID 40406158, 2025). "Using lentiviral transduction to achieve hepatic insulin expression, Elsner was able to essentially cure diabetes mellitus." (PMID 39858654, 2025). "Diabetes is a metabolic disorder characterized by insulin resistance and/or defects in insulin secretion." (PMID 40869350, 2025). "These include reduced HbA1c,15, 16, 17 reduced total daily dose (TDD) of insulin, weight loss, reduced hospital admissions for DKA or severe hypoglycaemia, improvements in treatment satisfaction and self‐reported diabetes‐related behaviours." (PMID 39676327, 2025). "Metabolic disturbances give rise to both insulin resistance and impaired insulin secretion, together with beta-cell dysfunction, which advances diabetes progression." (PMID 40225541, 2025). "Oxidative stress contributes significantly to diabetes progression by damaging β-cells, impairing insulin secretion, and reducing insulin sensitivity." (PMID 40429763, 2025). "Diabetes mellitus is a chronic metabolic disorder characterized by elevated blood glucose levels resulting from insufficient insulin secretion or impaired insulin action." (PMID 40988275, 2025). "Most (317 [81%]) were prescribed oral diabetes medicines, 105 (27%) were prescribed insulin, and 72 (18%) had prediabetes." (PMID 41114992, 2025). "Presently, various oral antidiabetic medications, such as insulin, sulphonylureas, metformin, α-glucosidase inhibitors, and troglitazone, are available for diabetes treatment." (PMID 40463898, 2025).
diabetes (continued). "A total of 37 participants with type 2 diabetes (20 male and 17 female, aged 70.2 ± 10.0 years with BMI 31.0 (28.0-34.0) kg/m2 and duration of diabetes for 15.2 ± 7.7 years) were switched from premixed insulin treatment to iDegLira." (PMID 41268167, 2025). "This study aimed to develop a simplified insulin medication literacy scale for patients with diabetes mellitus in China (Ch-InMLS), assess the level of insulin medication literacy, and evaluate its psychometric properties." (PMID 40242444, 2025). "Targeted attention should be directed toward individuals who are older, have a longer duration of diabetes, are receiving oral hypoglycemic or insulin therapy, have lower educational levels, or belong to low-income households." (PMID 40979703, 2025). "Closed-loop AI systems are in use for diabetes (e.g., adaptive insulin pumps), and mental health applications are increasingly leveraging digital phenotyping (e.g., Mindstrong)." (PMID 40510210, 2025). "Type 1 diabetes mellitus (T1DM) is a chronic autoimmune disease characterized by the targeted destruction of insulin-producing beta cells within the islets of Langerhans." (PMID 41373714, 2025). "The American Diabetes Association’s standards of medical care for patients with diabetes also recommend that when medical nutrition therapy, exercise, and glucose monitoring are ineffective at maintaining a normal blood glucose level, insulin may be given as a last resort." (PMID 39910543, 2025). "Participants receiving insulin therapy at baseline were more likely to be female, have a longer duration of diabetes and have a higher baseline HbA1c." (PMID 40036884, 2025). "In a streptozotocin (STZ) + nicotinamide-induced diabetic mouse model, myricitrin encapsulated in solid lipid nanoparticles improved hyperglycemia, insulin resistance, and pancreatic apoptosis." (PMID 40286055, 2025). "Post-transplant diabetes mellitus (PTDM): Managing PTDM involves the early initiation of insulin therapy, standard diabetes treatments such as GLP-1 agonists and SGLT2 inhibitors, and optimizing immunosuppressive regimens." (PMID 40218153, 2025). "Similar results showing a small proportion of insulin+/glucagon+ islet cells in normoglycemic conditions with an increase in their proportion in diabetes were obtained in rodents." (PMID 39860066, 2025). "Diabetes, a metabolic disease, is defined by persistent hyperglycemia, typically resulting from insufficient insulin secretion or impaired insulin action." (PMID 41018201, 2025). "Adipose tissue of diabetes-prone mice was insulin resistant based on the adipo-IR index and downregulation of key genes involved in insulin signalling." (PMID 41361331, 2025). "Dysregulation of mTOR activity in patients with obesity and diabetes affects insulin sensitivity and lipid metabolism." (PMID 40547482, 2025). "For example, the absorption of insulin differs between animals and humans, as does the amount needed to maintain diabetes." (PMID 40955783, 2025). "Innovations in non-invasive hormone therapy for diabetes include inhalable insulin formulations, such as PLGA microcapsules stabilized with mannitol." (PMID 40005989, 2025). "Connected insulin pens capture and report information on insulin doses and timings, with the goal of helping the person with diabetes to optimise treatment outcomes." (PMID 41039947, 2025). "By suppressing energy-intensive and ROS-generating pathways, DDIT4/REDD1 is vital for maintaining β-cell integrity and insulin secretory function during and after hypoxic episodes, such as those encountered in diabetes or during islet transplantation." (PMID 41440034, 2025). "Predictors of insulin discontinuation included shorter diabetes duration, lower baseline HbA1c, and lower insulin doses." (PMID 40277315, 2025).
diabetes (continued). "These include genetic defects affecting β-cell function or insulin action, as well as diseases of the exocrine pancreas such as cystic fibrosis and pancreatitis that can contribute to the development of diabetes." (PMID 40686811, 2025). "Diabetes Mellitus (DM) is a chronic metabolic disorder characterized by hyperglycemia due to absolute lack, inadequate insulin production, or insulin resistance (i.e., the cells of the body become unresponsive to the insulin’s effects)." (PMID 39996053, 2025). "Her blood glucose levels were stable once on an established dose, and she received insulin education and was discharged, with Diabetes Clinic follow-up planned." (PMID 40918801, 2025). "We would suggest designs where potential disease-modifying therapies are added as adjuncts to insulin therapy only 2–4 weeks after diabetes diagnosis in the animal models in order to replicate more closely the situation in human trials of these therapies." (PMID 40014914, 2025). "Insulin-treated diabetes affected 9.1% of patients, while autoimmune, thyroid, and chronic lung diseases occurred each in ~13%." (PMID 40724840, 2025). "In veterinary medicine, insulin therapy is also the mainstay for managing diabetes in dogs and cats, but with more limited options." (PMID 41012437, 2025). "These cases involved patients labeled having-diabetes within one month of PD onset, based on medication (e.g., insulin) or ICD-10 codes, despite HbA1c ≤ 6.5%." (PMID 41407881, 2025). "Estimated changes in insulin dosing with SGLT2 inhibitor therapy, showing overall among all countries regardless of sample size, and the subset of countries with N > 100 people with diabetes reporting insulin use." (PMID 40245017, 2025). "Probiotic species such as Lactobacillus, which supports glycemic control, and Akkermansia muciniphila, which enhances insulin sensitivity and reduces inflammation, are of particular interest in diabetes research." (PMID 40943103, 2025). "The prevalence of diabetes and pre-diabetes and the levels of insulin and insulin-resistance increased several-fold between the normal weight and morbidly obese groups in both sexes." (PMID 40077610, 2025). "Type 2 diabetes mellitus (T2DM), the most common form, is associated with obesity and involves either a gradual decline in insulin secretion by β-cells or a reduced sensitivity of the body’s cells to insulin (insulin resistance)." (PMID 40686811, 2025). "According to the Zambian formulary, the drugs that are used for the management of diabetes are insulin and oral hypoglycemic medicines, including medications used in the treatment of hypoglycemia." (PMID 40760593, 2025). "The weakened oxidative capacity is closely related to the pathogenesis of diabetes because mitochondrial dysfunction in pancreatic β cells can lead to reduced insulin secretion, thereby influencing glucose and lipid metabolism." (PMID 39859466, 2025). "Due to the major roles played by insulin disturbance in diabetes, insulin signaling is highly recommended for targeting diabetes and explored for developing new antidiabetic agents." (PMID 39846080, 2025). "For instance, the combination of the delivery model of insulin with glucose kinetics can be used to explore the application of microneedles in diabetes therapy." (PMID 39913061, 2025). "Meanwhile, moderate exercise up-regulates brain derived neurotrophic factor (BDNF) levels and restores insulin sensitivity as well as brain insulin signaling, thereby slowing diabetes-related cognitive decline." (PMID 41460428, 2025). "The glucose consumption ability of patients with diabetes is influenced by insulin function, and the decline in this consumption ability is an important aspect of the pathophysiological process of diabetes." (PMID 41375141, 2025). "The most commonly used diabetes mellitus treatment prior to transplant was insulin therapy (55.9%, n = 143), while 54.3% (n = 140) were receiving at least one oral anti‐glycaemic agent." (PMID 40664615, 2025).
diabetes (continued). "All patients in our series were managed with insulin therapy; two developed brittle diabetes requiring continuous glucose monitoring and frequent insulin titration." (PMID 41450393, 2025). "In terms of diabetes management, the majority of participants in both groups were receiving injectable insulin therapy - 20 participants (40%) in the NSD group and 19 participants (38%) in the PRP group." (PMID 40755619, 2025). "Despite the availability of new classes of glucose-lowering drugs, insulin therapy still represents a cornerstone of the treatment for type 2 diabetes mellitus (T2D), and many patients eventually require and benefit from insulin therapy." (PMID 39235480, 2025). "Type 1 diabetes results from an absolute deficiency of insulin, while T2DM stems from insulin resistance accompanied by a progressive decline in β-cell function." (PMID 41333024, 2025). "Clinicians should diagnose EIAS based on a history of hypoglycemia, exogenous insulin use, diabetes autoantibodies, and elaboratory results." (PMID 41585798, 2025). "The fundamental concept of nano bio-robotics for diabetes treatment involves creating a pancreatic “closed-loop” insulin secretion system which patients with diabetes have lost." (PMID 41280718, 2025). "Examine the effects of age of diabetes onset, metabolic control and type of insulin regimen on neurocognitive function in children and adolescents with type 1 diabetes." (PMID 40291285, 2025). "The top five predictors identified by SHAP analysis included TyG, Insulin therapy, HbA1c, Diabetes Course, HDL." (PMID 41293734, 2025). "Diabetes mellitus (DM) is a prevalent pathological disease that often requires the use of oral antidiabetic agents or subcutaneous insulin injections to achieve and sustain glycemic regulation." (PMID 39649678, 2025). "Nearly all health professionals, whatever their practice or speciality, now have contact with a significant number of insulin‐using people with diabetes." (PMID 40035222, 2025). "Their pleiotropic action supports the use of phytochemicals as anti-inflammatory insulin sensitizers in the dietary management of type 2 diabetes mellitus." (PMID 40563357, 2025). "Diabetes is a chronic metabolic disorder characterized by hyperglycemia, resulting from either insufficient insulin secretion or impaired insulin action." (PMID 40299682, 2025). "Regarding diabetes management, most PwDM used oral medication or insulin therapy, and 21.2% used a sensor to control blood glucose levels." (PMID 40140841, 2025). "Thereafter, the high-fat diet-induced obesity model mice further developed a pathology resembling human diabetes mellitus, also with markedly higher levels of blood glucose after insulin injection." (PMID 40703332, 2025). "For most patients living with diabetes, physical training also improves muscle mechanics, muscle insulin sensitivity, and glucose utilization through mitochondrial oxidation and storage as muscle glycogen." (PMID 39796621, 2025). "Lycopene, a potent lipid-soluble carotenoid antioxidant abundant in tomatoes, has shown notable preclinical efficacy in improving glucose metabolism, insulin sensitivity, and reducing oxidative stress, which are critical aspects in diabetes pathophysiology." (PMID 40563946, 2025). "Chronic inflammation and oxidative stress are critical contributors to impaired islet function and insulin sensitivity in diabetes." (PMID 40260393, 2025). "These challenges persist despite advances in technologies available to patients and families living with diabetes, including insulin pumps, insulin analogs, and continuous glucose monitoring (CGM) systems." (PMID 41049863, 2025). "Insulin secretagogue properties of 4-OHIle and anti-cancerous properties of diosgenin support its consumption for treatment of insulin resistance, cancer, diabetes, and obesity." (PMID 40083886, 2025).